EPCAM (epithelial cell adhesion molecule)
Diseases named in the same sentence as EPCAM in open-access papers (continued):
Sharing a sentence is not in itself a finding about the gene and the disease.
cancer (continued). "Our experiments were consistent with previous reports, demonstrating that PD-L1 positive CTC undetectable by EpCAM or keratins exist in cancer patients." (PMID 32466213, 2020). "This study has shown that intercalation of a common chemotherapeutic into a bifunctional aptamer generated a drug delivery vehicle, which is capable of transcytosing the BBB and specifically delivering its payload to EpCAM-positive cancer cells." (PMID 32027209, 2020). "In an autologous organoid/CTL co-culture derived from patients with PD-L1-positive tumors, organoids were sensitive to nivolumab treatment (condition 2), whereby the addition of PMN-MDSCs inhibited nivolumab-induced EpCAM+ cancer organoid death (condition 4)." (PMID 33348809, 2020). "EpCAM attracts attention as a target for cancer-related immunotherapy due to its abundant expression in solid tumors, although its expression in normal epithelia is low." (PMID 33081407, 2020). "Clinical studies on CTCs using CellSearch underscored the prognostic value of EpCAM-positive CTCs in various cancers." (PMID 32507912, 2020). "EpCAM is a cancer stem cell (CSC) marker, which is expressed in various epithelial carcinomas comprising ESCA." (PMID 32714406, 2020). "EpCAM will retain a central role as of anchor molecule in the enrichment of CTCs that harbor metastatic potential in advanced cancer patients." (PMID 32507912, 2020). "As such, EpCAM bears potential as a prognostic and therapeutic marker in carcinomas and during cancer progression and metastasis formation." (PMID 32507912, 2020). "Epithelial cell adhesion molecule (EpCAM) is commonly used as a surface marker for detecting CTCs in various cancers, including HCC." (PMID 33268834, 2020). "In this experiment, sumac significantly reduced expression levels of CD24, ALDH1, and EpCam in cancer cells." (PMID 33375383, 2020). "To investigate how GATA5 mechanistically stimulated Paclitaxel to suppress malignantbehaviors of HCC cells, we analyzed expression of the cancer stem cell reprogramminggenes, Nanog, EpCAM, c-Myc and Sox2 in the cells by Western blotting." (PMID 32779438, 2020). "Whole blood was first acquired from a cancer patient and incubated for 1 h with anti-EPCAM antibody-conjugated magnetic beads." (PMID 32486306, 2020). "Intraperitoneal infusion of catumaxomab effectively reduced ascites and eliminated EpCAM-positive cancer cells in the ascites fluid of OC patients." (PMID 32392820, 2020). "The dismal prognosis of this pathology is linked to the features of the HCC harbouring cancer stem cells (CSC), represented by EpCAM-expression." (PMID 33225916, 2020). "Strong expression of EpCAM promoted EMT and a cancer stem cell phenotype in association with increased migration and invasion, via the activation of AKT, mTOR, p70S6K, and 4EBP1." (PMID 32507912, 2020). "Preclinical studies demonstrated feasibility of the use of anti-EpCAM DARPin-toxin fusion protein for treatment of several types of cancer." (PMID 32392820, 2020). "Several publications demonstrated that EpCAM-specific antibodies can eliminate cancer cells by various mechanisms and detect DTC in the bone marrow of patients." (PMID 32507912, 2020). "The discovery of RIP of EpCAM and the generation of the signaling-active fragments EpEX and EpICD paved the way for a novel class of EpCAM inhibitors that target signaling in cancer and the metastatic cascade." (PMID 32507912, 2020). "While this discovery opens exciting perspectives about EpCAM function during development and in cancer, we still are at the very beginning of exploring this aspect of EpCAM biology." (PMID 32961790, 2020). "Recent findings indicated that the EpCAM has normal low expression healthy epithelial cells, while in cancer cells its expression become in higher levels (up to 1000-fold)." (PMID 32383027, 2020). "First reports of a transient EpCAM regulation in cancer progression came from xenotransplantation models." (PMID 32507912, 2020).
cancer (continued). "Recent research has shown a clear correlation between human cancers and high expression of EpCAM of human cancers." (PMID 32714406, 2020). "Adding to this, during epithelial mesenchymal transition EMT, down regulation of EpCAM is required for the invasion by cancer cells." (PMID 32212818, 2020). "Epithelial cell adhesion molecule (EpCAM) is a CTC marker in various cancer types, whereas cluster of differentiation 44 (CD44) is a GCSC marker." (PMID 33036473, 2020). "A high number of EpCAM-expressing CTCs has been correlated with reduced OS in different cancer types." (PMID 32764280, 2020). "EpCAM-based enrichment for CTC detection has provided a reliable prognostic tool in different cancers." (PMID 32764280, 2020). "In this review, we describe EpCAM biology and its role in the metastatic cascade and in targeted therapies in cancer." (PMID 32764280, 2020). "It is possibly needed to specifically delineate in the future studies that EpCAM supports cancer cells growth either via the soluble EpEX or cytoplasmic EpICD as it is already known that these two domains are both pro-oncogenic." (PMID 32046162, 2020). "We will also discuss the current updates on the roles of EpCAM especially in cell adhesion, cell signalling and additional insights on EpCAM functions in the cancer-related landscape." (PMID 32046162, 2020). "EpCAM-positive CTCs were most abundant in patients with metastatic ovarian cancer (65–680/mL) compared with other cancer species." (PMID 33327605, 2020). "EPCAM overexpression in cancer cells plays a critical role in cancer cell migration, proliferation, and differentiation, consequently imparting the potential to metastasize to cancer cells, after extravasation." (PMID 32486306, 2020). "The high expression of EpCAM in many cancer types would support cancer growth and progression because EpCAM involves modulating biological processes such as cell proliferation, differentiation, migration and invasion." (PMID 32046162, 2020). "In this review, we focus on the structural features of the EpCAM gene and protein as well as its post-translational modifications and relate them in the context of cancer." (PMID 32046162, 2020). "Increases in EpCAM expression have been correlated to cancer development and progression and increased proliferation, which is also evident in our results." (PMID 32545676, 2020). "TW-1 expressed various markers that are unique in stem cell, such as CD133, GSTP1, CD44, and EpCAM, which was identified as a cancer cell line with progenitor or stem cell-like properties." (PMID 33322441, 2020). "Their and our study demonstrated the usefulness of the EpCAM marker for the detection of early LNs cancer invasion." (PMID 32244422, 2020). "BC cells having high expression of EpCAM gain the ability to refract the RT efficacy by promoting cellular heterogeneity, enhanced plasticity within the cancer cell population, and thus pushing the cell fate more toward the CSC phenotype." (PMID 33490064, 2020). "Apart from EpCAM and cancer-specific antigens, currently developed CTC detection methods permit recognition of other CTC biomarkers of great clinical impact, such as programmed cell death ligand 1 (PD-L1)." (PMID 31936460, 2020). "EpCAM is down-regulated in many cancers, especially during the process of metastasis, when epithelial to mesenchymal transition (EMT) occurs." (PMID 32785154, 2020). "Non-malignant mammary cell spheres were also embedded in the hydrogels as the authors aimed at mimicking the interface between cancer cells and healthy cells by mediating the display of EpCAM." (PMID 32098281, 2020). "The expression of FLT4 and MET markers appeared to be associated predominantly with CK (+) cells, with the abundance of CK (+) EpCAM (-) phenotype being sharply elevated in cancer stage IA samples." (PMID 32899940, 2020).
cancer (continued). "We performed RNA sequencing (RNAseq) on CAF-S1 and CAF-S4 fibroblasts, and EPCAM+ cancer cells sorted from PTs and matched invaded LNs." (PMID 31964880, 2020). "More studies will be focused on investigating how UBE2C regulating these cancer markers including ALDH1A2, CD44, CD166 and EpCAM and the relationship between these cancer markers for cancer stemness in vitro." (PMID 32899896, 2020). "There was an inverse correlation between EpCAM expression level and the EpCAM promoter DNA methylation status in these cancer types." (PMID 32046162, 2020). "Nonetheless, the subset of isolated large EpCAM+, CK+ tdEVs from blood of cancer patients has a similar prognostic power to CTCs in metastatic prostate, breast, colorectal, and nonsmall cell lung cancer patients and can complement CTCs in the CellSearch assay." (PMID 32582525, 2020). "EpCAM is considered a common marker protein of epithelial-derived cancers and is involved in several cancer-relevant cellular mechanisms like proliferation and cancer cell stemness." (PMID 33322643, 2020). "This growth stimulating property of EpCAM in mice early development sets a paradigm and foreshadows its role in human cancer cell proliferation, invasion and metastasis." (PMID 32046162, 2020). "EpCAM was also targeted with T cell-engaging antibodies designed to connect cytotoxic T cells with cancer cells for redirected lysis." (PMID 32507912, 2020). "This heterogeneous expression and downregulation of EpCAM has been described in different cancer entities." (PMID 32197486, 2020). "In contrast, combinations of several markers have proved to be of superior diagnostic value, such as the combination of EMMPRIN/EpCAM/MUC1/EGFR, which reliably separated cancer patients from healthy controls with a high AUC value of 0.85." (PMID 32731639, 2020). "I review here the currently available data, comment on possible connections with other properties of EpCAM, and discuss the potential significance in the context of cancer invasion." (PMID 32961790, 2020). "EpCAM is a key molecule that engages in cancer cell signaling, differentiation, proliferation, migration, progression, and invasion." (PMID 32599893, 2020). "This is in agreement with most in-vitro studies that suggests EpCAM is important in maintaining epithelial barrier and is further indicative of how it can function in disease like cancer to promote pro-metastatic properties." (PMID 32046162, 2020). "In the present study, the Fc of IgM was fused to EpCAM to generate polymeric protein structures as a cancer vaccine in the Chinese cabbage expression system." (PMID 33143243, 2020). "In the frames of the Cancer-ID program, we reanalyzed digitally stored FM image data sets of retrospective clinical studies acquired after EpCAM enrichment." (PMID 32582525, 2020). "Pre-clinical as well as clinical studies targeting EpCAM+ cancer cells using monoclonal antibodies or CAR constructs have been performed to date using co-culture and xenograft approaches." (PMID 32849491, 2020). "Nevertheless, since EpCAM is found to be enriched on the circulating exosomes in several cancer types, utilization of specific antibody against EpCAM has been among the strategies developed to detect and isolate exosomes for downstream investigation." (PMID 32046162, 2020). "In cancer tissue, EpCAM is homogeneously expressed on the cell surface, while in epithelia it is expressed on the basolateral side." (PMID 32849491, 2020). "Recent studies have revealed that EpCAM is over-expressed in a variety of human cancers, including HCC." (PMID 32212818, 2020). "EpCAM-201 is the predominant isoform which is corroborated by the TCGA large scale cancer transcriptomic findings." (PMID 32046162, 2020). "EpCAM has been shown to be ubiquitously expressed on epithelial tumours and on EVs from these cancers." (PMID 33121160, 2020).
cancer (continued). "Immunotherapy with the trifunctional anti-EpCAM x anti-CD3 antibody catumaxomab was approved in 2009 by the European Commission for the treatment of malignant ascites in cancer patients with EpCAM-expressing tumors." (PMID 32392820, 2020). "Due to the overexpression of EpCAM in cancer and its accessibility on the cell surface, EpCAM is of high interest to be developed as a marker for prognosis, diagnosis and therapeutic intervention for epithelial cancers." (PMID 32046162, 2020). "As the EpCAM is highly expressed on normal epithelia and epithelial cancer cells and inattentive on blood cells it is commonly used for capturing of epithelial CTCs." (PMID 33182636, 2020). "Other studies then showed the role of EpCAM in the regulation of cancer cell proliferation, migration, and invasion." (PMID 32764280, 2020). "Decades after its discovery on cancer cells, EpCAM was found to be highly expressed on murine and human ESCs, and on murine embryonic germ cells." (PMID 32507912, 2020). "Au NPs encapsulated with the antitumour drug paclitaxel-coated by anti-EpCam antibodies-modified red blood cell membranes show increased cancer-targeting ability due to anti-EpCam antibodies." (PMID 32872399, 2020). "Recent findings have shown the oncogenic potential of EpCAM and its link to bad prognosis in many cancer types." (PMID 33490064, 2020). "The EpCAM cancer antigenic protein can be used to prevent and inhibit cancer; hence, it is a vaccine candidate." (PMID 33143243, 2020). "For that, we used magnetic beads coated with a monoclonal antibody towards the human Epithelial Cell Adhesion Molecule (EpCAM), a surface molecule highly expressed in carcinomas, especially in PC patients." (PMID 32630240, 2020). "Forty years ago, EpCAM was first described as a major epithelial carcinoma antigen that is recognized by monoclonal antibodies that bind specifically to human colorectal carcinoma cells." (PMID 32764280, 2020). "EpCAM was originally identified as a marker for carcinoma and its role includes diverse processes such as signalling, cell migration, proliferation, and differentiation." (PMID 33343836, 2020). "This explains why our patients #5 and #6 with synchronic CRCs displayed different EPCAM expression in their carcinomas." (PMID 33003511, 2020). "EpCAM is also a promising therapeutic target, as numerous studies indicate its role as a cell surface marker for various types of carcinoma." (PMID 33081407, 2020). "Expression patterns, regulation, and the multiple functions of EpCAM in normal epithelia, in carcinoma, and in pluripotent stem cells are reviewed." (PMID 32507912, 2020). "EpCAM, a carcinoma cell-surface marker protein and a therapeutic target, has been primarily addressed as a cell adhesion molecule." (PMID 32486423, 2020). "A role of EpCAM in differentiation was reported in pluripotent embryonic stem cells (ESCs), progenitor cells, and carcinoma stem cells." (PMID 32507912, 2020). "EpCAM received considerable attention as a prognostic marker based on its strong expression in various carcinomas and their metastases as compared to normal epithelia of the same localization." (PMID 32507912, 2020). "High expression of EpCAM was reported on epithelial cancer cells in primary and metastatic lesions, as well as on some undifferentiated CSCs of major carcinoma entities." (PMID 32599893, 2020). "While, EPCAM, which is overexpressed in most human carcinomas, abrogates E‐cadherin‐mediated cell‐cell interaction,55MCAM overexpression is associated with increased expression of epithelial‐mesenchymal transition (EMT) biomarkers and cell motility." (PMID 32888398, 2020). "First evidence for a correlation of EpCAM in proliferation and differentiation surfaced in 1994 and 1996 in keratinocytes, transformed epithelial cells, and carcinoma cell lines." (PMID 32507912, 2020).
cancer (continued). "Cells that co-stained for both ALDEFLUOR and EpCAM (for marking carcinoma cells) were sorted along with those that were EpCAM-positive and ALDEFLUOR-negative." (PMID 32316543, 2020). "EpCAM, also known as CD326, is a 40 kDa type I membrane glycoprotein frequently expressed in human carcinomas, and involved in cell proliferation by linking to components of the Wnt signaling pathway and regulators of the cell cycle." (PMID 33081407, 2020). "Frequent and high-level expression of EpCAM on various carcinomas (98 out of 131 tested) and metastases, and a correlation with clinical outcome qualified it as prognostic marker and therapeutic target." (PMID 32507912, 2020). "In malignant tumors, EpCAM is stably expressed or even up-regulated and contributes to malignant progression of disease." (PMID 31361893, 2019). "EpCAM, together with CD44v6, has been shown to have an increased expression in Panc1 cancer stem-like cells." (PMID 31048929, 2019). "We compared the CTC recovery rates, WBC depletion rates, and CTC purity of the PosCTC-μChip and the NegCTC-μChip, using blood samples spiked with cancer cells with different expression levels of EpCAM." (PMID 31181790, 2019). "Epithelial cellular adhesion molecule (EpCAM) was also proposed as a cancer-related factor in other malignancies." (PMID 31718609, 2019). "Up to now, several methodologies for cancer cell analysis have been built based on specific immune recognition between the monoclonal antibody of Anti-EpCAM and the EpCAM on cancer cell membranes." (PMID 31010258, 2019). "Epithelial cell adhesion molecule encodes epithelial cell adhesion molecule, also known as CD326, is usually high expressed in cancer tissues and participates in intercellular adhesion limitation, cell signaling, migration, proliferation, and differentiation." (PMID 31598425, 2019). "The CellSearch and Adnatest platforms both make use of magnetic beads attached to antibodies to EpCAM, but Adnatest employs additional cancer-specific antibodies depending on the requirement." (PMID 31174404, 2019). "Cancer cells from fresh or frozen specimens were enriched by the anti-EpCAM antibody-conjugated magnetic beads, plated on Matrigel-coated plate and cultivated under the optimized culture conditions." (PMID 31248002, 2019). "Even though the immune checkpoints such as EpCAM and PD-1 are common targets for immunotherapy in various types of cancer, there is limited data recording their expression by human immune cells and relevant importance in the peripheral blood." (PMID 31354723, 2019). "The CellSearch® Profile technology allows a reliable, standardized, and automated enrichment of EpCAM-positive cancer cells." (PMID 31514447, 2019). "EpCAM-based approaches for CTC detection have significantly contributed to validate the clinical relevance of CTCs in various cancer entities." (PMID 31225512, 2019). "The device has been tested on cancer cell line-spiked blood samples using the EpCAM antibody, and the capture efficiency was 62 ± 7% with a purity of 51 ± 18%." (PMID 31088479, 2019). "EpCAM‐positive and EpCAM‐negative tumors shared 398 probes, corresponding to 348 genes that were differentially expressed between cancer and control tissues." (PMID 31267557, 2019). "Detection of soluble forms of EpCAM in blood serum of cancer patients has reported disappointing results, notably due to a lack of correlation of with important clinical end-points like overall survival in most studies." (PMID 31225512, 2019). "In this review, we summarize the current knowledge on the biological properties of EpCAM with emphasis on mechanisms involved in cancer progression and discuss the clinical implications of these findings for the clinical use of EpCAM as a diagnostic marker." (PMID 31225512, 2019).